ADM (adrenomedullin)
Diseases named in the same sentence as ADM in open-access papers (continued):
Sharing a sentence is not in itself a finding about the gene and the disease.
tumor (continued). "Adrenomedullin has also been proposed as a mediator of tumor angiogenesis." (PMID 36374225, 2023). "In addition, our data revealed a novel mechanism by which adrenomedullin promotes its formation by tumor cells." (PMID 36374225, 2023). "Consistent with a role of tumor cell–derived adrenomedullin in endothelial and tumor cell proliferation under co-culture conditions, MLECs showed increased proliferation when exposed to conditioned medium of B16-F10 cells, an effect lost after knock-down of endothelial Gαs and CALCRL." (PMID 36374225, 2023). "Additionally, we observed high expression of pSMAD3 and ACVR2B in tumor‐associated ADM regions, suggesting a potential role of activin A in tumor‐mediated ADM." (PMID 37083240, 2023). "It remains to be evaluated whether promoting endothelial CCL2 formation in adrenomedullin-producing tumors is a strategy to reduce tumor growth." (PMID 36374225, 2023). "This is based on the ability of adrenomedullin to induce pro-angiogenic effects in endothelial cells in vitro as well as on the observation that the expression levels of adrenomedullin in tumors correlate with tumor angiogenesis in vivo." (PMID 36374225, 2023). "In addition, for the intersected genes of two features, tumor-secreted adrenomedullin (ADM) is recognized as a type of regulatory polypeptide driving both tumor and lymph node angiogenesis." (PMID 36091041, 2022). "ADM shows expression in human lung, breast, brain, prostate, colon, and other tumor cell lines." (PMID 36183123, 2022). "Of these, ADM, DCBLD2, EREG, ITGA5, MIF, MMP14, and TREM1 were associated with poor prognosis and significantly increased in tumor, while BTG2 was related to favorable prognosis and decreased in tumor." (PMID 35002712, 2021). "Studies have revealed that adrenomedullin derived from TAMs promotes tumor growth through activation of the endothelial nitric oxide synthase (eNOS) signaling pathway, and inhibition of adrenomedullin receptors on TAMs ultimately suppresses tumor growth." (PMID 34207035, 2021). "Thus, ADM is endowed with properties that can efficiently contribute to activation of distinct pathways promoting tumor growth: lipolysis and browning." (PMID 32819314, 2020). "ADM, a multifunctional peptide, is highly expressed in several tumors, including those of the brain, breast, colon, prostate, and lung, and plays important roles in tumor angiogenesis, cell growth, and survival." (PMID 33340396, 2020). "It has also been shown that the degree of adrenomedullin peptide expression correlates with GBM tumour grade, with highest expression in grade IV tumours, where adrenomedullin is localised in proximity to large necrotic areas together with vascular endothelial growth factor (VEGF)." (PMID 30777055, 2019). "However, a recent study illustrated an anti-angiogenic role of miR-126 during tumor angiogenesis by targeting a pro-angiogenic gene adrenomedullin (ADM)." (PMID 29415727, 2018). "ADM, VEGF, and HIF-1 are all associated with tumor angiogenesis, but whether ADM modulates angiogenesis and interacts with VEGF and HIF-1 in EOC remains unknown." (PMID 28091613, 2017). "Our results confirmed that ADM is an upstream molecule of HIF-1α/VEGF, so we suppose ADM may be involved in the regulation of other angiogenic “classic” factors to promote tumor angiogenesis." (PMID 28091613, 2017). "Moreover, we found that myelomonocytic cells depletion displayed a stronger effect on tumor angiogenesis and growth compared to the pro-angiogenic effect of ADM." (PMID 27391260, 2016). "Reanalysis of these raw data showed that upregulation of ADM expression and its downstream pathway may play a role in tumor resurgence following VEGF inhibition." (PMID 27556517, 2016). "ADM expression by cancer cells promotes tumor growth, so combination therapy with sunitinib and an ADM receptor antagonist may have important implications for RCC treatment." (PMID 27556517, 2016).
tumor (continued). "Aryl hydrocarbon receptor repressor gene directly regulates ADM expression under normal physiologic conditions but may also play a role during the early stages of tumour genesis in the lung." (PMID 25623364, 2015). "Adrenomedullin has been identified as a tumor survival factor and exerts antimicrobial properties." (PMID 23894342, 2013). "Additionally, several lines of evidence have suggested that inhibiting the ADM pathway with antibodies or antagonists directed against ADM or ADM receptors can reduce angiogenesis and tumor cell proliferation in mouse cancer models." (PMID 23520487, 2013). "The other six genes with more than two-fold upregulation in more than five tumours arrayed were CCNG2 in 30 tumours, NDRG1 in 18 tumours, PFKFB3 in 17 tumours, RNAse4 in 10 tumours, Adrenomedullin (ADM) in eight tumours and Glucose transporter 1 (GLUT-1) in six tumours." (PMID 16052224, 2005). "Adrenomedullin, a secreted protein, may also prove to be useful as a marker of hypoxic tumours in the urine." (PMID 16052224, 2005). "However, a significant positive correlation was found between tumour size and plasma ADM levels (r=0.641, P=0.017)." (PMID 14612905, 2003). "Adrenomedullin overexpressing tumours are characterised by an increased vascularity." (PMID 14612905, 2003). "With progressive ADM expression decline, transcriptional levels of pro-tumorigenic inflammatory cytokines IL1B and CX3CL1 demonstrated gradual downregulation, suggesting elevated ADM expression may accelerate tumor progression through pro-inflammatory microenvironment enrichment." (PMID 41450464, 2025). "Also, tumor cell proliferation was unaffected by suppressed endothelial ADM expression." (PMID 36374225, 2023). "To test whether Gs-mediated signaling in endothelial cells regulates the release of a diffusible endothelial factor, which in turn controls the formation of adrenomedullin in tumor cells, we cultured tumor cells in the presence of supernatants from endothelial cells with or without loss of Gαs." (PMID 36374225, 2023). "Furthermore, CCL2 inhibited adrenomedullin formation in tumor cells through its receptor CCR2." (PMID 36374225, 2023). "This may underline the functional differences between tumor and developmental angiogenesis and indicates that endothelial adrenomedullin signaling pathway is not involved in developmental retinal angiogenesis." (PMID 36374225, 2023). "To identify the major source of adrenomedullin responsible for the proliferation of endothelial and tumor cells in the co-culture model, we studied the effect of an adrenomedullin knock-down in endothelial or in tumor cells on the proliferation of both co-cultured cell types." (PMID 36374225, 2023). "Therefore, an antagonist gel that inhibits both CLR/RAMP1 and 2 may be useful for blocking CGRP- and ADM-mediated tumor growth and metastasis in patients." (PMID 36569288, 2022). "Furthermore, ADM is overexpressed in various types of cancer, including pancreatic and prostate cancer, and appears to act as an autocrine and/or paracrine mediator that promotes tumor growth." (PMID 27391260, 2016). "However, blocking adrenomedullin inhibited sunitinib-resistant tumor growth." (PMID 27556517, 2016). "To detect the potential role of ADM in BTC, we analysed the expression levels of ADM in human BTC tissues and adjacent non‐tumour tissues through performing qRT‐PCR experiments." (PMID 40074697, 2025). "Compared with adrenomedullin, there is considerably less information available concerning the expression patterns and functions of CGRP in tumours." (PMID 36835377, 2023). "Adrenomedullin (ADM) is a small circulating peptide produced and secreted by tumor cells, but also by endothelial cells, macrophages, mast cells, and vascular smooth muscle cells." (PMID 36835166, 2023). "Our findings show tumor-promoting roles of adrenomedullin and identify CCL2 as an angiocrine factor controlling adrenomedullin formation by tumor cells." (PMID 36374225, 2023).
tumor (continued). "In contrast to adrenomedullin (and CGRP), minimal information is available concerning the expression patterns of CALCRL and the various RAMP isoforms in human tumours." (PMID 36835377, 2023). "According to previous reports, the functions of CD44, ADM, TYMS, and MKI67 are primarily in promoting the Warburg effect and tumor growth in various cancers, while the function of those four genes in DTC has rarely been reported." (PMID 35528004, 2022). "Two weeks after inoculation, when the tumor volumes reached ~200 mm3, we examined the expressions of HIF-1α and the HIF-1 target genes ADM and PDK1 in the apyrase and shHIF-1α groups to verify the successful establishment of the xenograft models." (PMID 35236823, 2022). "Among these, JMJD1A was found to regulate a subset of hypoxia-induced genes, ADM, EDN1, HMOX1, and GDF15, and was important for the growth of tumour xenografts in a hypoxic environment." (PMID 34572020, 2021). "Once in the tumor, TAMs secrete pro-angiogenic factors such as VEGF-A, TGF-β, fibroblast growth factor-2 (FGF-2), CCL18, semaphorin 4D (Sema4D), adrenomedullin (ADM), and placental growth factor (PlGF)." (PMID 33783686, 2021). "More specific, ADM, NDRG1, and TUBB6 were down-regulated, while other 10 genes were up-regulated in tumor samples compared with normal control." (PMID 33344235, 2020). "Earlier studies have shown ADM22-52, small moleculeantagonist, anti-ADM antibody, and anti-CLR/RAMP antibodies block the growth and/ormetastasis of tumor xenografts in animal models." (PMID 31150417, 2019). "Many of the tumor tissues in mice injected with MART1 plasmid + Ad, MART1 plasmid + AdM, or MART1 plasmid + AdMGshT displayed expression of adenovirus-specific protein, whereas mice in the PBS-treated group did not." (PMID 28178658, 2017). "The GSE64052 and GSE76068 microarray datasets indicated that ADM and ERK/MAPK were significantly upregulated, which contributed to sunitinib-resistant tumor growth." (PMID 27556517, 2016). "TAMs secrete a wide range of pro-angiogenic mediators, including basic fibroblast growth factor, thymidine phosphorylase, urokinase-type plasminogen activator (uPA), and adrenomedullin (ADM), to facilitate tumor angiogenesis." (PMID 25125485, 2014). "Adrenomedullin (ADM) is an angiogenic factor that has also been shown to be a mitogen and a hypoxia survival factor for tumour cells." (PMID 14612905, 2003). "In addition, the angiogenic potential of ADM overexpressing cells might increase the probability of tumour cells trapped in the lymphatic capillaries to induce neovascularisation and to give rise to macroscopic tumour growth." (PMID 14612905, 2003). "Additionally, CSC markers ADM, DLGAP5, S100A9, and TNFRSF11B showed consistent overexpression at both RNA and protein levels in tumor samples, with significantly lower expression in normal tissues." (PMID 40243557, 2025). "In addition, hypoxia-MSCs destabilize endothelial junctions via adrenomedullin (ADM), which leads to the formation of hyperpermeable tumor vasculature, whereas VE-adhesin adhesion junctions are critical for restoring vascular integrity." (PMID 40800581, 2025). "Furthermore, protein levels of ADM were determined by protein blotting in 8 pairs of human BTC specimens and their matched non‐tumour tissues." (PMID 40074697, 2025). "For instance, the hypoxic conditions characteristic of the tumor microenvironment result in the upregulation of ADM expression via HIF-1, suggesting that targeting HIF-1 could impede tumor progression." (PMID 40565016, 2025). "Moreover, they can produce factors that promote the growth of blood vessels within the tumor, such as VEGF-A, VEGF-C, and adrenomedullin, thereby supplying oxygen for tumor development." (PMID 38650924, 2024). "In addition, we show that adrenomedullin inhibits the formation of the endothelial angiocrine factor CCL2 which, in turn, can suppress adrenomedullin formation by tumor cells." (PMID 36374225, 2023).
tumor (continued). "CGRP, ADM, and ADM2 have been shown to promote vascular development and tumor growth." (PMID 36569288, 2022). "JMJD1A increases or maintains expression of certain genes under hypoxia by reducing H3K9 demethylation of specific hypoxia-responsive promoters, including ADM, EDN1, HMOX1, and GDF15, resulting in increased expression of these genes and favouring tumour cell growth." (PMID 34572020, 2021). "Lysophospholipids and adrenomedullin stimulate insertion of the channel into the plasma membrane, and the subsequent TRPV2-mediated Ca2+ influx increases invasiveness of tumor cells via the direct regulation of key proteases such as MMP2, MMP9, and cathepsin B." (PMID 31288452, 2019). "At the same time, LDHA, ADM, SLC2A1 and CA9 were also decreased in EP300 knockdown ESCC cells, indicating that EP300 may promote tumor growth and progress via hypoxia in ESCC." (PMID 31632486, 2019). "The cellular and molecular mechanisms by which adrenomedullin (AM) blockade suppresses tumor neovessels are not well defined." (PMID 25924235, 2015). "Further studies comparing T2w-derived whole-body tumor burden, WB-MTV and WB-TLG will shed light on the usefulness of these techniques for providing an imaging biomarker correlating with known circulating biomarkers such as adrenomedullin, MIA or SOX9." (PMID 26625155, 2015). "Gene expression analysis showed that several genes involved in tumor development and metastasis (EGR1, COX2, MALAT1, AKAP12, ADM) were similarly induced in CSC and cisplatin-resistant H460 cells, in agreement with a close similarity between these two cell populations." (PMID 24961511, 2014). "Additionally, ADM expression is significantly upregulated in the TME under hypoxic conditions through the hypoxia-inducible factor-1 (HIF-1) pathway, indicating that ADM plays a crucial role in tumor adaptation to hypoxic environments." (PMID 40565016, 2025). "According to our analyses, ADM exhibited positive correlation with metabolic reprogramming, particularly in purine (PPAT, GMPS, RRM1, and RRM2) and pyrimidine (CAD and UMPS) metabolic pathways, suggested that it played an important role in tumor cell metabolic adaptation." (PMID 40547013, 2025). "As ADM concentrations reach nanomolar levels or higher, there is an upregulation in the expression of angiogenic factors such as the vascular endothelial growth factor (VEGF), monocyte chemoattractant protein-1 (MCP-1), and basic fibroblast growth factor (bFGF) within the MC/tumor complex." (PMID 40565016, 2025). "Consequently, ADM is capable of inducing VEGF expression in cancer cells via the JNK/AP-1 signaling pathway, thereby promoting cancer progression through the enhancement of tumor angiogenesis." (PMID 40565016, 2025). "In vitro experiments further substantiate these findings, as ADM knockout inhibits proliferation, migration, and invasion of OSCC cells, reduces mRNA levels of MMP2, and induces compensatory upregulation of RAMP2, therefore suppressing tumor cell migration and invasion." (PMID 38256104, 2024). "In addition to the pro-angiogenic effect, we found that adrenomedullin also suppressed the formation of endothelial CCL2 through cAMP-PKA, and thereby resulted in the suppression of CCL2-induced inhibition of adrenomedullin formation by tumor cells." (PMID 36374225, 2023). "In addition, the reduced adrenomedullin expression and proliferation of control tumor cells cultured with endothelial cells lacking Gαs were normalized in tumor cells lacking CCR2." (PMID 36374225, 2023). "Suppression of adrenomedullin expression in LLC1 tumor cells also resulted in reduced tumor growth in vivo, and loss of tumor derived adrenomedullin, but not of endothelial adrenomedullin, reduced tumor angiogenesis and cell proliferation." (PMID 36374225, 2023).
tumor (continued). "In addition, we show that adrenomedullin acting on endothelial cells further stimulates formation of adrenomedullin in tumor cells by inhibiting the endothelial formation and release of CCL2, which acts as an angiocrine factor to inhibit adrenomedullin expression by tumor cells." (PMID 36374225, 2023). "In addition, suppression of adrenomedullin expression in tumor cells, but not in MLECs, led to reduced adrenomedullin expression and release in the co-culture." (PMID 36374225, 2023). "In addition, we found that these ligands secreted by hypoxia-related GBM cell types, namely, MES1-like tumor cells, MES2-like tumor cells, and TAM-1, may stimulate angiogenesis via, for example, ADM, ANGPTL4, GDF15, and VEGFA." (PMID 35669791, 2022). "Therefore, CALCRL mediates the occurrence and development of tumor cells such as CGRP and ADM." (PMID 34712139, 2021). "In agreement with findings that ROS may regulate angiogenesis and tumor growth through HIF-1α and VEGF, over-expression of Nrf2 in tMSC led to a diminished hypoxic response through destabilization of HIF-1α and reduced VEGFA and ADM expression." (PMID 24491031, 2014).